TRAV21 (T cell receptor alpha variable 21)
Description:
V region of the variable domain of T cell receptor (TR) alpha chain that participates in the antigen recognition. Alpha-beta T cell receptors are antigen specific receptors which are essential to the immune response and are present on the cell surface of T lymphocytes. Recognize peptide-major histocompatibility (MH) (pMH) complexes that are displayed by antigen presenting cells (APC), a prerequisite for efficient T cell adaptive immunity against pathogens. Binding of alpha-beta TR to pMH complex initiates TR-CD3 clustering on the cell surface and intracellular activation of LCK that phosphorylates the ITAM motifs of CD3G, CD3D, CD3E and CD247 enabling the recruitment of ZAP70. In turn ZAP70 phosphorylates LAT, which recruits numerous signaling molecules to form the LAT signalosome. The LAT signalosome propagates signal branching to three major signaling pathways, the calcium, the mitogen-activated protein kinase (MAPK) kinase and the nuclear factor NF-kappa-B (NF-kB) pathways, leading to the mobilization of transcription factors that are critical for gene expression and essential for T cell growth and differentiation. The T cell repertoire is generated in the thymus, by V-(D)-J rearrangement. This repertoire is then shaped by intrathymic selection events to generate a peripheral T cell pool of self-MH restricted, non-autoaggressive T cells. Post-thymic interaction of alpha-beta TR with the pMH complexes shapes TR structural and functional avidity.
Synonyms: TCRAV21S1; TCRAV23S1
Gene: T-cell receptor variable (V) gene on chromosome 14 (22,052,514 to 22,053,056, forward strand). Ensembl gene ENSG00000211801.
Subcellular location: Cell membrane
Gene Ontology:
Biological process: response to bacterium
Cellular component: plasma membrane
Homologues: Orthologues: chimpanzee TRAV21 (82% identical), macaque TRAV21 (80% identical), dog TRAV21 (62% identical). Paralogues in human: TRAV17 (51% identical), TRAV20 (49% identical), TRAV36DV7 (46% identical), TRAV24 (45% identical), TRAV39 (45% identical), TRAV6 (44% identical), TRAV10 (41% identical), TRAV7 (41% identical), TRAV5 (40% identical), TRAV34 (38% identical), TRAV13-2 (37% identical), TRAV13-1 (36% identical), and 11 more.
Diseases named in the same sentence as TRAV21 in open-access papers:
TRAV21 is named in the same sentence as 3 diseases in open-access papers, as found by Europe PMC text mining. Sharing a sentence is not in itself a finding about the gene and the disease. The quoted sentences say what the papers report.
infection (2 papers, 2024 to 2025). The state of being infected such as from the introduction of a foreign agent such as serum, vaccine, antigenic substance or organism. "Several common TRA and TRB pairs, such as TRAV1-2/TRAJ33, TRAV21/TRAJ49, TRBV6-4/TRBD2/TRBJ2-3, and TRBV5-1/TRBD1/TRBJ2-7, were consistently detected from the primary infection (PI) through the convalescent phase (HC) and into the reinfection phase (RI)." (PMID 41209021, 2025). "The DEG analysis showed that LAIR2, CD7, KLRB1, TYROBP, TRAV19, TRAV21, and TRBV6-5 were upregulated in group E VS group B both breakthrough infection by BA.5.2." (PMID 39835127, 2024).
tumour (1 paper, 2022). "The Vβ and Jβ genes with differential usage in our study were also inconsistent with this study, except for the TRAV21 gene, which was higher in tumour tissues than in peritumour tissues in both studies." (PMID 36463235, 2022).
TRAV21 also shares sentences with these, for which no sentence is quoted: COVID-19 (1 paper).